STIMATE-MUSTN1 (STIMATE-MUSTN1 readthrough)
Synonyms: TMEM110-MUSTN1
Gene: Protein-coding gene on chromosome 3 (52,833,121 to 52,897,562, reverse strand). Ensembl gene ENSG00000248592.
Genetic constraint (gnomAD): Loss-of-function variants: 27 observed, 47.33 expected, observed/expected ratio (o/e) 0.57, 90% interval 0.42 to 0.79. The upper end of that interval is the gene's LOEUF score, 0.79, which puts it in group 3 of 6, group 1 being the genes least tolerant of losing a copy. Missense variants: 411 observed, 478.77 expected, observed/expected ratio (o/e) 0.86, 90% interval 0.79 to 0.93. Synonymous variants: 203 observed, 191.92 expected, observed/expected ratio (o/e) 1.06, 90% interval 0.94 to 1.19.